CIP2A (cellular inhibitor of PP2A)
Diseases named in the same sentence as CIP2A in open-access papers (continued):
Sharing a sentence is not in itself a finding about the gene and the disease.
breast carcinoma (continued). "Genistein treatment of MCF-7-C3 and T47D breast cancer cells resulted in dysregulation of the human oncoprotein known as the carcinogenic inhibitor of protein phosphatase 2A (CIP2A), suggesting that CIP2A is a target of genistein responsible for inducing apoptosis and growth suppression." (PMID 40427522, 2025). "Similarly, although LINC00665 functions as a pro-tumor factor in breast cancer (BC), its small peptide CIP2A-BP can lead to suppressed abilities of migration and invasiveness of BC cells." (PMID 37347740, 2023). "Thus, the results support the potential benefits of CIP2A inhibition for breast cancer treatment via activity of PP2A." (PMID 37097392, 2023). "Moreover, CIP2A has recently been shown to interact with the TOPBP1 complex during mitosis in breast cancer cells." (PMID 36999590, 2023). "Moreover, CIP2A expression has also been described as a predictive marker of recurrence in tamoxifen-treated breast cancer patients." (PMID 35329936, 2022). "However, the clinical and therapeutic relevance of the CIP2A/AKT interplay in breast cancer remains to be fully clarified." (PMID 35329936, 2022). "Furthermore, our results indicate that CIP2A is a key determinant of p-AKT in breast cancer, since 82.5% of CIP2A-overexpressing cases also had high p-AKT levels." (PMID 35329936, 2022). "CIP2A has been studied as a potential therapeutic target in several cancers, including neuroblastoma, colorectal cancers, renal cell carcinoma, and breast cancer." (PMID 35454859, 2022). "In this line of thinking, we hypothesized that breast cancer patients could benefit from the use of pharmacologic CIP2A/AKT inhibitors such as FTY720." (PMID 35329936, 2022). "Thus, we investigated both p-AKT and CIP2A levels in a cohort of 220 breast cancer patients, observing that high p-AKT levels strongly correlated with high CIP2A expression and that both markers were predictive of poor outcome." (PMID 35329936, 2022). "To investigate role of CIP2A on breast cancer cell growth, we performed CIP2A gene silencing experiment and found that CIP2A levels were indeed downregulated with two different siRNA sequences (siR1 and siR2), leading to complete and partial knocking down results, respectively." (PMID 33948919, 2021). "We indicated that even low concentrations of EVE could increase CIP2A expression in EVE‐resistant breast cancer cells." (PMID 32810922, 2020). "Furthermore, increased CIP2A degradation through autophagy was seen in breast cancer cells upon mTORC1 inhibition (e.g., using rapamycin)." (PMID 31214504, 2019). "In addition, the use of autoantibodies as serum biomarkers for CIP2A showed promising results in breast cancer patients." (PMID 31214504, 2019). "However, in estrogen receptor (ER)-positive breast cancer cells, estradiol (E2) was able to increase CIP2A protein levels through the ERα." (PMID 31214504, 2019). "In particular, CIP2A overexpression has been reported in approximately 60% of ErbB2+ breast cancer samples and may have potential as a clinical predictor for lapatinib responsiveness." (PMID 28938602, 2017). "Therefore, we examined the role of CIP2A in lapatinib-induced anti-cancer effects in ErbB2-overexpressing SKBR3 human breast cancer cells and 78617 cells, which are derived from spontaneous mammary tumors of MMTV-ErbB2 transgenic mice." (PMID 28938602, 2017). "Together, these data suggest that CIP2A may serve as a promising target in molecular therapeutics due to its important role in breast cancer etiology." (PMID 28938602, 2017). "Future combinational therapies using lapatinib and CIP2A-targeting agents may be promising breast cancer treatment strategies." (PMID 28938602, 2017). "Together, these data suggest that CIP2A plays an important role in breast cancer cells and that targeting CIP2A could be a new therapeutic option." (PMID 26824320, 2016).
breast carcinoma (continued). "Prior studies have indicated the role of CIP2A in senescence induction, that CIP2A may render breast cancer cells resistance to senescence induction." (PMID 26824320, 2016). "In addition, CIP2A promotes the malignant growth of breast cancer cells and correlates with poor prognosis." (PMID 26824320, 2016). "Moreover, future studies evaluating PP2A phosphorylation after knock-down of SET or CIP2A are warranted to assess their relevance in regulating PP2A activity in breast cancer." (PMID 25726524, 2015). "Additionally, CIP2A signature reveals the c-MYC dependency of CIP2A-regulated phenotypes and its association with breast cancer subtypes." (PMID 25726524, 2015). "Moreover, CIP2A has been reported as a useful predictive marker of response to vinca alkaloid-containing chemotherapy in HER2-negative breast cancer patients." (PMID 25726524, 2015). "Our results support the potential of CIP2A as a therapeutic target in breast cancer treatment." (PMID 25228280, 2014). "CIP2A expression may be a potential biomarker for chemotherapeutic sensitivity and prognosis in breast cancer." (PMID 25015035, 2014). "CIP2A signature revealed the MYC dependency of CIP2A-regulated phenotypes in the breast cancer." (PMID 25015035, 2014). "Interestingly, the traditional chemotherapeutic agent doxorubicin has been shown to downregulate CIP2A expression, and increased CIP2A expression confers doxorubicin resistance in breast cancer cells." (PMID 25228280, 2014). "Therefore, the potential application of the new CIP2A inhibitory mechanism of tamoxifen as part of a combination treatment strategy with other anti–breast cancer agents is worth further investigation." (PMID 25228280, 2014). "Together, these data suggest that CIP2A has an important role in breast cancer cells and that targeting CIP2A could be a new therapeutic approach." (PMID 25228280, 2014). "Moreover, in our recent studies, we found that CIP2A is an important molecular determinant of bortezomib-induced apoptosis in leukemia cells and in breast cancer cells." (PMID 25228280, 2014). "Future studies correlating response to tamoxifen with downregulation and/or pretreatment expression levels of CIP2A in breast cancer patients may help to establish a clinical role for CIP2A as a predictive factor in breast cancer." (PMID 25228280, 2014). "CIP2A expression has been shown to correlate with disease aggressiveness in breast cancer." (PMID 22537901, 2012). "Moreover, it has been shown that the traditional chemotherapeutic agent doxorubicin downregulates CIP2A expression and that increased CIP2A expression confers doxorubicin resistance in breast cancer cells." (PMID 22537901, 2012). "Future studies correlating response to bortezomib with downregulation and/or pre-treatment expression levels of CIP2A in breast cancer patients may help to establish a clinical role for CIP2A as a predictive factor in breast cancer." (PMID 22537901, 2012). "Future studies defining CIP2A as a useful therapeutic biomarker for breast cancer patients, as well as the detailed mechanism by which bortezomib inhibits CIP2A may lead to further progress in the development of molecular-targeted therapy for TNBC." (PMID 22537901, 2012). "Previous study showing CIP2A expression in breast cancer has mainly been based on mRNA expression." (PMID 22537901, 2012). "In addition, a new study further confirmed that the overexpression of CIP2A was a key contributory event of AKT phosphorylation in the correlation analysis of p-AKT and CIP2A in 220 clinical samples, and emphasized that the CIP2A-AKT axis is a promising therapeutic target for breast cancer." (PMID 36911405, 2023). "More interestingly, LINC00665 can encode a special micropeptide (CIP2A-BP) to inhibit the progression of three negative breast cancers or act as a ceRNA that is involved in regulating the LINC00665/AGTR1/miR-34a-5p axis and other biological behaviours in glioma." (PMID 35174152, 2022).
breast carcinoma (continued). "Thus, several compounds such as cucurbitacin B and everolimus in the ER-positive subtype, together with lapatinib, arctigenin, and the erlotinib derivative TD52 in the TN subtype, have demonstrated to exert their antitumor properties in breast cancer, downregulating both CIP2A and p-AKT." (PMID 35329936, 2022). "Moreover, CIP2A has been involved in response to drugs such as bortezomib, genistein, or doxorubicin, and it has been proposed as a potential therapeutic target in breast cancer." (PMID 35329936, 2022). "Therefore, we performed MDA-MB-231 xenografts that were treated with FTY720 in order to both investigate the potential therapeutic value of the CIP2A/AKT signaling as a novel molecular target in breast cancer and validatein vivo the role of CIP2A as a p-AKT regulator." (PMID 35329936, 2022). "When MCF-7-C3 and T47D breast cancer cells were medicated with genistein, the cancerous inhibitor of protein phosphatase 2A (CIP2A), a human oncoprotein, was dysregulated, leading to the hypothesis that CIP2A was a genistein target in causing growth inhibition and apoptosis." (PMID 34698063, 2021). "Moreover, the expression level of CIP2A is quite low in healthy human tissues, therefore targeting CIP2A may represent a potential therapeutic strategy for anti-breast cancer therapies." (PMID 33948919, 2021). "High expression of CIP2A was associated with significantly reduced OS in patients with luminal A breast cancer [hazard ratio = 1.98 (1.18–3.32), P < 0.01] but not in patients with basal‐like breast cancer [hazard ratio = 0.63 (0.33–1.20), P = 0.156]." (PMID 32810922, 2020). "Moreover, our previous studies also revealed that CIP2A plays a critical role in the sensitivity of TD52 (an erlotinib derivative) as well as bortezomib in breast cancer and liver cancer, suggesting that CIP2A signaling is a promising target for cancer therapy." (PMID 30063110, 2018). "Moreover, it has been recently reported that CIP2A deficient mice are resistant to mammary tumorigenesis, the existence of a positive feedback loop involving CIP2A and E2F1 which defines senescence sensitivity of breast cancer cells, and the CIP2A modulation of mTORC1 and authophagy in this disease." (PMID 25726524, 2015). "In gastric and breast cancers, increased MYC expression with concurrent CIP2A expression correlate with more resilient cancer cells." (PMID 41155727, 2025). "For example, Cancerous Inhibitor of Protein Phosphatase 2A (CIP2A) is highly expressed in OSCC cell lines, in addition to lung and breast cancers." (PMID 40096320, 2025). "CIP2A-BP inhibits the oncogene CIP2A, thereby inhibiting multiple oncogenic signaling pathways and CIP2A-BP-abrogated lung metastases in the MMTV-PyMT mouse breast cancer model." (PMID 38203767, 2024). "Altogether, the clinical and therapeutic importance of the CIP2A/AKT axis as well as the relevance of CIP2A as a key AKT regulator and plausible molecular target in breast cancer must be fully clarified, which represents our main objective in this study." (PMID 35329936, 2022). "For example, several erlotinib derivatives were able to reduce CIP2A levels and increase PP2A activity in breast cancer and hepatocellular carcinoma cells via disrupting the interaction between the transcription factor Elk1 and the CIP2A promotor." (PMID 31214504, 2019). "CIP2A and PP2A are expected to be very effective therapeutic targets in AI-resistant breast cancers." (PMID 29805747, 2018). "We and others have shown that SET and CIP2A, two oncogenic inhibitors of PP2A, are overexpressed in various cancers, including hematopoietic malignancies and breast cancer." (PMID 27705940, 2016). "In our previous studies, we demonstrated that pharmacological decrease of CIP2A, thereby increased PP2A activity and subsequent inactivation of the p-Akt signaling, inhibited proliferation and induced apoptosis in breast cancer cells." (PMID 26824320, 2016).
breast carcinoma (continued). "These cell lines were chosen based on their CIP2A and SET overexpression levels and because they represent aggressive breast cancer phenotypes (MDA-MB-231: triple negative; BT-474: HER-2)." (PMID 25726524, 2015). "To determine its clinical relevance, we quantified SET, CIP2A and PP2A phosphorylation in a series of 230 breast cancer patients, observing that PP2A inhibition is a recurrent molecular event that determines shorter overall and event-free survival." (PMID 25726524, 2015). "We report here that PP2A inhibition is a frequent event in breast cancer and identified PP2A hyperphosphorylation together with SET and CIP2A overexpression as molecular mechanisms that cooperate to inactivate this phosphatase." (PMID 25726524, 2015). "Altogether, these results would indicate that the molecular mechanism of action of FTY720 in breast cancer cells involves PP2A activation through its dephosphorylation and CIP2A downregulation together with inhibition of AKT and ERK signaling." (PMID 25726524, 2015). "Here, we show that PP2A inhibition is a common event in breast cancer and identified PP2A phosphorylation and deregulation SET and CIP2A as molecular contributing mechanisms to inactivate PP2A." (PMID 25726524, 2015). "In concordance with our findings, a recent work has shown that both CIP2A and SET are frequently co-overexpressed with c-MYC in breast cancer cell lines." (PMID 25726524, 2015). "To investigate the prevalence and clinical significance of PP2A inhibition, we quantified SET, CIP2A and phosphorylated PP2A (p-PP2A) expression in a cohort of 230 patients with early breast cancer mainly treated with anthracyclin-based adjuvant chemotherapy." (PMID 25726524, 2015). "With regard to MYC, these results both validate CIP2A's role in regulating MYC-mediated gene expression and provide a plausible novel explanation for the high MYC activity in basal-like and HER2+ breast cancers." (PMID 25015035, 2014). "To validate the role of CIP2A signaling in mediating the apoptotic effect of bortezomib in breast cancer cells, we first generated MDA-MB- 231-CIP2A and MDA-MB-468-CIP2A cells which constitutively express ectopic CIP2A." (PMID 22537901, 2012). "Finally, CIP2A-BP+/+ mice were further crossed with breast cancer-prone MMTV-PyMT mice, obtaining MMTV-PyMT;CIP2A-BP+/+ mice." (PMID 39054345, 2024). "SET, CIP2A, and pS62-MYC proteins are commonly overexpressed in human breast cancers." (PMID 37097392, 2023). "Consistent with our findings, although lncRNA LINC00665 has been reported to exert a promoting effect on the progression of breast cancer, its 52-aa peptide CIP2A-BP functions as an anti-tumor factor in TNBC via the PP2A/PI3K/AKT/NF-κB pathway by binding the oncogene CIP2A." (PMID 37285335, 2023). "Altogether, our findings further support the relevance of CIP2A overexpression as a molecular alteration that leads to p-AKT upregulation, and also indicate that p-AKT plays a predictive role inresponse to doxorubicin in breast cancer patients." (PMID 35329936, 2022). "SET and CIP2A mRNA levels were high in breast cancer cells compared with the immortalized but nontransformed human breast epithelial cell line MCF10A." (PMID 30341686, 2018). "Our data point to CIP2A and PP2A as novel therapeutic targets for AI-resistant breast cancer." (PMID 29805747, 2018). "Moreover, SET and CIP2A were found to be endogenous inhibitors of PP2A, and SET, CIP2A, and pS62-MYC proteins are commonly overexpressed in human breast cancers." (PMID 28124725, 2017). "In concordance with our findings in prostate cancer, CIP2A overexpression and PP2A (Y307) hyperphosphorylation were identified as two main contributing alterations with relevant clinical and therapeutic implications in breast cancer." (PMID 26023836, 2015).
breast carcinoma (continued). "To study the clinical significance of CIP2A, we further examined CIP2A and p-Akt expression in tumor samples from 123 patients with ER-negative breast cancers (including 53 (43.1%) with HER2-positive breast cancers)." (PMID 25228280, 2014). "We previously found that bortezomib induced apoptosis in triple-negative (negative expression of ER, PR and HER2) breast cancer cells through downregulation of CIP2A and p-Akt, suggesting that CIP2A is a target of bortezomib." (PMID 25228280, 2014). "Cancerous inhibitor of protein phosphatase 2A (CIP2A), a well-known oncoprotein that inhibits tumor suppressor protein phosphatase 2A (PP2A), is overexpressed in about 70% of various cancer types, such as non-small cell lung cancer (NSCLC), GC, and breast cancer." (PMID 41155583, 2025). "As CIP2A has been reported to be involved in doxorubicin sensitivity, and that p-AKT represents a CIP2A downstream effector, we performedex vivoanalyses to investigate whether p-AKT could be involved in the appearance of resistance to doxorubicin in breast cancer." (PMID 35329936, 2022). "However, our results on the effect of CIP2A on cell apoptosis are inconsistent with results of previous studies; for instance, in cervical cancer, breast cancer, and hepatocellular carcinoma, CIP2A knockdown does not induce significant apoptosis." (PMID 27144172, 2016). "Results from studies in different organ-type cancers including breast cancer indicated that CIP2A, rather than independently/ exclusively accomplishing the tumorigenic effect in cells, forms an important component of the “oncogenic nexus” in concert with PP2A and c-MYC." (PMID 25015035, 2014). "CIP2A is expressed in only very few normal tissues but it is overexpressed with very high incidence (40–80%) in various human cancer types such as head and neck squamous cell carcinomas (HNSCC), colon carcinomas, gastric carcinomas, breast carcinomas and non-small cell lung cancer." (PMID 21445343, 2011). "Since CIP2A overexpression has been previously involved in doxorubicin resistance, and since AKT represents a CIP2A downstream effector, we hypothesized that upregulation of p-AKT could play a relevant role determining doxorubicin response in breast cancer patients." (PMID 35329936, 2022). "In current study, CIP2A silencing leads to decreased cell viability in MCF-7 cells in addition to doxorubicin-mediated effects, suggesting that targeting CIP2A may represent a potential therapeutic strategy to treat breast cancer patients who developed resistance to doxorubicin." (PMID 33948919, 2021). "Thus, we observed a reduced PP2A activity in all the five breast cancer cell lines analyzed, identifying PP2A hyperphosphorylation and SET and CIP2A overexpression in all cases, which prompted us to hypothesize that these could be relevant contributing mechanisms to inhibit PP2A in breast cancer." (PMID 25726524, 2015). "Moreover, the authors studied publically available datasets (cBioPortal) and reported that PP2A activation status could be deregulated in more than 50% of basal breast cancer tumors due to alterations affecting PP2A subunits or deregulation of endogenous PP2A inhibitors such as SETBP1, SET or CIP2A." (PMID 25726524, 2015). "The presence of five cases without CIP2A overexpression and high p-AKT confirmed our previous observations in the cohort of 220 cases about the existence of other molecular mechanisms distinct fromCIP2A involved in p-AKT regulation in breast cancer." (PMID 35329936, 2022).